APP (amyloid beta precursor protein)
Diseases named in the same sentence as APP in open-access papers (continued):
Sharing a sentence is not in itself a finding about the gene and the disease.
Alzheimer disease (continued). "To investigate the effects of moderate ethanol exposure on glucose metabolism in APP/PS1 mice, an early-onset Alzheimer’s disease (AD) mouse model, we employed an fluoro-deoxy-glucose (FDG)-micro-positron emission tomography (PET)." (PMID 40098048, 2025). "In this study, the APP/PS1 double transgenic AD mouse model was used to investigate the pharmacodynamic effects and mechanisms of the dual-target liposome complex AD808 in Alzheimer’s disease." (PMID 40732267, 2025). "In the context of Alzheimer’s disease, legumain phosphorylation at S226 by SRPK2 led to accumulation of cytoplasmic legumain, promoting cleavage of tau, APP, and SRPK2 itself." (PMID 38199506, 2024). "To address this, we have conducted an in-depth analysis utilizing APP/PS2 transgenic mice, recognized as a well-established mouse model for Alzheimer’s disease." (PMID 38473814, 2024). "Presenilin‐1 is a component of the gamma secretase complex and is involved in the proteolysis of several integral membrane proteins such as amyloid precursor protein (APP), being therefore a focus of interest for Alzheimer's disease research." (PMID 38013241, 2024). "Changes in three distinct genes—amyloid precursor protein (APP), amyloid beta (A4), presenilin 1 (PSEN1), and presenilin 2 (PSEN2)—have been pinpointed as the primary culprits behind early-onset Alzheimer’s disease (EOAD)." (PMID 38785945, 2024). "The amyloid precursor protein (APP), a vital element of the protein processing system, plays a significant role in the origin of Alzheimer’s disease." (PMID 38397800, 2024). "APLP1, APLP2, and APP are well-established substrates of β-site amyloid precursor protein cleaving enzyme 1 (BACE1), playing crucial molecular roles in Alzheimer’s disease." (PMID 38370359, 2024). "Disruption of endosomal sorting complexes required for transport (ESCRT) -mediated APP trafficking and ubiquitination by ubiquitination factor E4B (UBE4B) dysregulation contributes to Aβ accumulation in Alzheimer’s disease." (PMID 38347638, 2024). "In some diseases such as Alzheimer’s disease, the overexpression of UCHL1 appears to interact with the amyloid precursor protein (APP) and regulate the production of β-amyloid peptides." (PMID 38612616, 2024). "Here, we compare the effects of sleep deprivation in young wild-type mice and their APP/PS1 littermates, a murine model of Alzheimer’s disease." (PMID 39541211, 2024). "β-amyloid is a product of APP that is also associated with a decrease in established Alzheimer’s disease; however, it is not clear what plasma APP levels are found in those at risk of developing Alzheimer’s disease and whether an elevation may precede the subsequent decrease in established disease." (PMID 38256230, 2024). "Due to the higher abundance of Aη peptides in the brain than the well-established Aβ peptides and their potential involvement in impairing long-term potentiation (LTP), it is intriguing to speculate that this non-canonical APP processing pathway may be implicated in Alzheimer’s disease." (PMID 38992438, 2024). "Examples of these proteins include amyloid precursor protein (APP) Aβ and C-terminal fragments (CTF) in Alzheimer’s disease (AD), mutant α-synuclein in Parkinson’s disease (PD), and polyglutamine (polyQ)-expanded mutant HTT (mHtt) in Huntington’s disease (HD)." (PMID 39582602, 2024). "To investigate the role of NOX4 in Alzheimer’s disease, we conducted immunofluorescence staining to measure the levels of NOX4 protein in GFAP-positive astrocytes in the cortical region of APP/PS1 transgenic mice and wild-type (WT) mice." (PMID 38956702, 2024). "An additional 31 genes in the Alzheimer’s Disease KEGG pathway lose rhythmicity with aged serum; these include amyloid precursor protein (APP) and apolipoprotein E (APOE)." (PMID 37808824, 2024). "In an Alzheimer's disease (AD)‐affected brain, the releasing of a small peptide, APP‐C31, from the amyloid precursor protein (APP) is increased." (PMID 37949680, 2024).
Alzheimer disease (continued). "Amyloid-β peptides (Aβs) are produced via cleavage of the transmembrane region of the amyloid precursor protein (APP) by γ-secretase and are responsible for Alzheimer’s disease." (PMID 36835396, 2023). "In the pathway unification database, SRC, EGFR, MAPT, APP and PRKCA were identified as key molecules in the pathway of Alzheimer’s disease." (PMID 37010714, 2023). "The effect of folic acid supplementation on present Alzheimer’s disease pathology was determined through measurements of serum Aβ (amyloid beta) 40, Aβ 42, Aβ 42/Aβ 40, APP (amyloid precursor protein) mRNA, PS1 (presenilin 1) mRNA, and PS2 mRNA." (PMID 37764675, 2023). "Three of these predicted targets (i.e., APP, BACE1, and MAPT) were found to be highly interacting proteins (i.e., hub proteins) in the constructed Alzheimer’s disease PPI network." (PMID 37367890, 2023). "Overall, this work introduces a new method to limit APP misprocessing and its cellular consequences without directly targeting secretase activity, offering a novel tool to reduce cognitive decline in pathologies such as Alzheimer’s disease and HIV-associated neurocognitive disorders." (PMID 36576708, 2023). "Our results prove that the allosteric inhibition of the phosphorylation of APP by ROCK2 is a new, feasible option in the fight against Alzheimer’s disease." (PMID 37445593, 2023). "Amyloid Precursor Protein (APP) and its cleavage processes have been widely investigated in the past, in particular in the context of Alzheimer’s Disease (AD)." (PMID 37047617, 2023). "The Alzheimer disease pathway is the second-ranked signaling pathway, and 5 key targets, CASP9, APP, NOS2, NOS1 and PTGS2, are enriched in this pathway." (PMID 37904435, 2023). "Furthermore, presenilins, which are part of the molecular machinery that processes APP, when mutated are responsible for most of the cases of familial AD; more than 70 different mutations in presenilin 1 (PS1) have been associated with inherited early onset Alzheimer’s disease." (PMID 37240836, 2023). "This is consistent with indentation studies in the cortex of APP/PS1 mutant mice, MRE studies in mice, and with MRE experiments in humans with Alzheimer’s disease that report softening of cortical brain regions." (PMID 37547743, 2023). "The selective knock-out of Lrp1 in astrocytes results in an accumulation of Aβ-peptide in the CNS and exacerbates disease development in APP/PS1 mice, an established model of Alzheimer disease." (PMID 37383546, 2023). "For example, the amyloid precursor protein (APP) gene, which plays a crucial role in forming amyloid plaques in Alzheimer’s disease, has an ortholog in C. elegans called apl-1." (PMID 37511895, 2023). "Since protein aggregation has been strongly implicated in the pathogenesis of Alzheimer’s disease and related disorders, but not previously linked to endogenous Appl function, we focused on validation and mechanistic exploration of the control of protein homeostasis by APP." (PMID 37923712, 2023). "Recently, it was shown that amyloid precursor protein (APP), a protein known to play a key role in the development of Alzheimer’s disease, is a newly identified receptor of Slit." (PMID 38298831, 2023). "The amyloid precursor protein (APP) is a ubiquitously expressed type 1 transmembrane protein mostly known for serving as a precursor to the amyloid-β peptide (Aβ), a culprit in Alzheimer disease (AD)." (PMID 35275192, 2022). "Caspase activation and the aberrant processing of amyloid precursor protein (APP), both essential processes in Alzheimer’s disease, have been demonstrated in a rat model of chronic ocular hypertension." (PMID 35028240, 2022). "Curcumin therapy improved spatial learning and memory in APP/PS1 mice, a model of Alzheimer’s disease, suggesting its neuroprotective qualities." (PMID 35684340, 2022). "Another relationship was found between FMRP and the amyloid precursor protein (APP), linking the pathophysiology of the FXS with Alzheimer’s disease." (PMID 35456004, 2022).
Alzheimer disease (continued). "The amyloid precursor protein (APP) is liable for the formation of Aβ peptides through its sequential proteolytic cleavages and has a central role in the growth of Alzheimer’s disease." (PMID 36014565, 2022). "Therefore, the present work aimed to investigate whether cholesterol metabolism was altered by age and RSV supplementation in the brain and blood serum of SAMP8 mice—an animal model of aging and Alzheimer’s disease—and their potential link with the amyloidogenic pathway of APP." (PMID 35886936, 2022). "PrPC additionally controls the expression of the amyloid precursor protein APP and of the Aβ generating enzyme BACE1, and regulates the levels of Aβ, whose accumulation is a central event in Alzheimer’s disease." (PMID 35962130, 2022). "Interestingly, activation of autophagy may be more effective in changing the neuroplasticity phenomena at conditions of pathological cellular endophenotypes related to accumulation of pathoproteins in APP/PS1 model of Alzheimer’s disease, such as cellular senescence." (PMID 36776770, 2022). "Intriguingly, APP (4621st → 24th) and LRRK2 (2629th → 25th) that are involved in Alzheimer’s disease and Parkinson’s disease, respectively, were suggested as highly probable candidates by GWAB." (PMID 36291657, 2022). "The metabolism of amyloid precursor protein (APP; Entrez gene ID: 351) into aggregation-prone amyloid-β (Aβ) peptides is proposed to be an early upstream factor in the pathogenesis of Alzheimer’s disease (AD)." (PMID 36578089, 2022). "IPA-induced aryl hydrocarbon receptor (AhR) activation inhibited neuroinflammation in APP/PS1 mice, a mouse model of Alzheimer’s disease (AD)." (PMID 36079724, 2022). "Amyloid precursor protein (APP) is a type 1 transmembrane glycoprotein that is widely recognized for its involvement in the pathogenesis and progression of Alzheimer’s disease (AD), and neuronal homeostasis." (PMID 36142659, 2022). "The mechanistic relationship between amyloid-beta precursor protein (APP) processing and mitochondrial dysfunction in Alzheimer’s disease (AD) has long eluded the field." (PMID 36104602, 2022). "Amyloid precursor protein (APP) is another relevant substrate of MT5-MMP, which holds a central position in Alzheimer’s disease (AD) pathogenesis." (PMID 35277173, 2022). "Evidence suggests that β-secretase (BACE1), which cleaves Amyloid Precursor Protein (APP) to form sAPPβ and amyloid-β, is elevated in Alzheimer's disease (AD) brains and biofluids and, thus, BACE1 is a therapeutic target for this devastating disease." (PMID 36056033, 2022). "Related to Alzheimer’s disease (AD), β-secretase (BACE) and its cleavage target amyloid precursor protein (APP) are shuttled through the retromer complex." (PMID 34370162, 2022). "As a model of early Alzheimer’s Disease, we used SH-SY5Y-APP695 cells; these cells are transfected with neuronal APP, which leads to increased production of cerebral Aβ, a neurotoxic peptide expressed in AD." (PMID 36012451, 2022). "This study demonstrates the effects of verbenalin on amyloid-beta (Aβ) peptide generation in Swedish mutant amyloid precursor protein (APP)-overexpressing Neuro2a cells (SweAPP/N2a) and in Alzheimer’s disease (AD) animal models." (PMID 36557811, 2022). "The TgF344-AD rat is unique in its manifestation of amyloid and tau pathology despite only expressing mutant APP and PS1, and therefore closely replicates human Alzheimer’s disease." (PMID 35434622, 2022). "Amyloid precursor protein (APP) and Tau are pathological hallmarks of Alzheimer’s disease (AD), and both proteins are legumain substrates." (PMID 36555634, 2022). "In Alzheimer’s disease, FKBP12 and amyloid precursor protein (APP) interplay has been suspected to affect Aβ peptides expression." (PMID 35087512, 2021).
Alzheimer disease (continued). "Our study demonstrates that PBMT, as a viable therapeutic strategy, directs the adult hippocampal APP/PS1 NSCs differentiate towards neurons, which has great potential value for ameliorating the drop of AHN in Alzheimer’s disease mice." (PMID 34116709, 2021). "The generation of amyloid β-peptides (Aβ) via sequential cleavages of APP by β-secretase (BACE1) and the presenilin/γ-secretase complex is central to the initiation of Alzheimer’s disease (AD)." (PMID 33571524, 2021). "Alzheimer’s disease is a striking example where amyloids are formed by the Aβ-peptide, a fragment of a large transmembrane protein APP (amyloid precursor protein)." (PMID 34827606, 2021). "As a result, we found prominent signal molecules such as APP, CASP3, and MAPK1, as well as key signal pathways like Alzheimer's disease and serotonergic synapses." (PMID 34977242, 2021). "The APPswe/PS1dE9 transgenic mouse (hereafter referred to as the “APP/PS1 mouse”) harbors mutant mouse/human APP (Swedish K595N/M596L) and PS1 genes (PS1-dE9) and is commonly used as an animal model of Alzheimer’s disease." (PMID 34737707, 2021). "APP is rapidly degraded by UPS in response to ER stress, leading to the formation of β-amyloid (Aβ), the main pathological marker of Alzheimer’s disease." (PMID 34249948, 2021). "In an Alzheimer’s disease model of C. elegans, overexpression of APL-1, the C. elegans ortholog for human Amyloid Precursor Protein (APP), led to reduced body length and resulted in locomotion defects." (PMID 34387338, 2021). "However, in Alzheimer’s disease, mitochondrial mass is reduced due to impaired mitochondrial biogenesis and low expression of PGC-1α, NRF1, and NRF2 as was demonstrated in human hippocampal neurons as well as in cells overexpressing APP causing familial Alzheimer’s disease." (PMID 33925080, 2021). "Secreted amyloid precursor protein-alpha (sAPPα), a metabolite of the parent amyloid precursor protein (APP) has been previously shown to enhance hippocampal LTP as well as memory formation in both normal animals and in Alzheimer’s disease models." (PMID 33867938, 2021). "While in human neuroblastoma cells (SHSY5YAPP+), CBD demonstrated neuroprotective properties by promoting ubiquitination of the amyloid precursor protein (APP), which is an indicator of cellular changes in the brain of patients with Alzheimer’s disease." (PMID 33927630, 2021). "APP and APLP are known to be intimately involved in the pathogenesis and progression of Alzheimer’s disease and to play important roles in neuronal homeostasis and development and neural transmission." (PMID 34066808, 2021). "Rd, a Chinese herb, may be a promising treatment drug for Alzheimer′s disease (AD) and is also reported to be related to several pathological changes, including the deposition of Aβ and tau hyperphosphorylation in AD as it decreases the deposition of tau hyperphosphorylation in APP transgenic mice." (PMID 34987593, 2021). "It is interesting that the mRNA coding for the amyloid precursor protein (APP), a key factor in Alzheimer’s disease (AD) pathogenesis, was also found at synapses." (PMID 33569760, 2021). "The function of the amyloid precursor protein (APP) is not fully understood, but its cleavage product amyloid beta (Aβ) together with neurofibrillary tangles constitute the hallmarks of Alzheimer’s disease (AD)." (PMID 34475508, 2021). "The Amyloid Precursor Protein (APP) is involved in the regulation of multiple cellular functions via protein-protein interactions and has been most studied with respect to Alzheimer’s disease (AD)." (PMID 34318654, 2021). "Among these substrates, the amyloid precursor protein (APP) has been the most studied, as generation of aggregation-prone amyloid β-protein (Aβ) is a defining feature of Alzheimer’s disease (AD)." (PMID 33450968, 2021).
Alzheimer disease (continued). "In vitro studies have shown that HSV-1 is capable of upregulating the processing of amyloid-beta precursor protein (AβPP), increasing Aβ, suggesting the possibility that the infection with HSV can contribute to Alzheimer’s Disease (AD)." (PMID 34916908, 2021). "Amyloid precursor protein (APP), upon proteolytic degradation, forms aggregates of amyloid β (Aβ) and plaques in the brain, which are pathological hallmarks of Alzheimer’s disease (AD)." (PMID 34440715, 2021). "We analyzed LRP3 expression in middle-aged individuals (MA) and in cases with Alzheimer’s disease (AD)-related pathology, and the relation of LRP3 with APP." (PMID 34727970, 2021). "Endocytosis of the amyloid precursor protein (APP) is critical for generation of β-amyloid, aggregating in Alzheimer's disease." (PMID 32065241, 2020). "Hypoxia-pre-conditioned MSC-derived exosomes ameliorated cognitive decline by rescuing synaptic dysfunction and regulating inflammatory responses in APP/PS1 mice, a model of Alzheimer’s disease." (PMID 31979113, 2020). "Aplp1 and Aplp2 are members of the amyloid precursor protein (APP), which is the source of the neurotoxic amyloid beta (Aβ) peptide involved in Alzheimer’s disease (AD)." (PMID 32759773, 2020). "Preliminary PET/CT imaging studies with [18F]FPEB were conducted in a transgenic model of Alzheimer's Disease (AD) using B6C3-Tg(APPswe,PSEN1dE9)85Dbo/J (APP/PS1) mice, and data were compared with age-matched wild-type (WT) B6C3F1/J control mice." (PMID 32098347, 2020). "Dysregulated protein secretion and shedding are linked to neurologic and psychiatric diseases, including neurodegeneration, e.g., APP, APOE, SORL1, and TREM2 in Alzheimer's disease (AD), or the prion protein (PRNP) in prion disease." (PMID 32954517, 2020). "PhenT additionally appears to regulate key proteins (APP and α‐synuclein) posttranscriptionally, as well as core gene sets (eg, AID and Blalock Alzheimer's Disease Up) involved in neuronal survival and neurodegeneration." (PMID 31828969, 2020). "Genetic and epidemiological studies have found that variations in the amyloid precursor protein (APP) and the apoliopoprotein E (APOE) genes represent major modifiers of the progressive neurodegeneration in Alzheimer’s disease (AD)." (PMID 32580938, 2020). "In aged APP/PS1 mice (8–9 months old), a model of Alzheimer’s disease, the effective coupling between hippocampus and cortex during the occurrence of SWRs involves different cortical areas than in WT mice." (PMID 33382724, 2020). "In this study, the mouse Alzheimer’s Disease RT2 Profiler PCR Array was used to analyze the BaP-induced alternations of gene expression profiles in the cortex of both WT and APP/PS1 mice." (PMID 32867800, 2020). "Herein, we showed that the expression of miR-338-5p decreased in APP/PS1 mice, accompanied by the elevation in the expression level of amyloid β, which indicated a reverse relationship between Alzheimer’s disease progression and miR-338-5p." (PMID 33087587, 2020). "Primarily, we found several aging (klotho, major vault 1, gelsolin, huntingtin, and fragile X mental retardation protein) and Alzheimer’s disease (ADAM10, apoE receptor, ChAT, APP, and PSEN1; most of these are also involved in aging) related sequences." (PMID 32449011, 2020). "Notch and the amyloid precursor protein (APP) and are undoubtedly the best-studied γ-secretase substrates because of their role in cancer and Alzheimer’s disease (AD) and therefore became the focus of increasing studies as an attractive therapeutic target." (PMID 33343338, 2020). "The amyloid precursor protein (APP) has been extensively studied as the precursor of the β-amyloid (Aβ) peptide, the major component of the senile plaques found in the brain of Alzheimer’s disease (AD) patients." (PMID 32327470, 2020).